C1orf174 (chromosome 1 open reading frame 174)
Synonyms: RP13-531C17.2
Tractability: PROTAC: its protein half-life has been measured.
Gene: Protein-coding gene on chromosome 1 (3,889,125 to 3,900,293, reverse strand). Ensembl gene ENSG00000198912.
Subcellular location: Nucleus
Subcellular location (Human Protein Atlas): Nucleoplasm
Gene Ontology:
Molecular function: protein binding
Cellular component: nucleoplasm; nucleus
Genetic constraint (gnomAD): Loss-of-function variants: 14 observed, 19.91 expected, observed/expected ratio (o/e) 0.7, 90% interval 0.46 to 1.1. The upper end of that interval is the gene's LOEUF score, 1.1, which puts it in group 4 of 6, group 1 being the genes least tolerant of losing a copy. Missense variants: 305 observed, 316.52 expected, observed/expected ratio (o/e) 0.96, 90% interval 0.88 to 1.06. Synonymous variants: 100 observed, 122.88 expected, observed/expected ratio (o/e) 0.81, 90% interval 0.69 to 0.96.
Homologues: Orthologues: chimpanzee C1H1orf174 (98% identical), macaque C1H1orf174 (93% identical), mouse A430005L14Rik (65% identical), dog C1orf174 (63% identical), rat C5h1orf174 (61% identical), pig C1orf174 (59% identical), guinea pig C1orf174 (57% identical), tropical clawed frog c7h1orf174 (30% identical), zebrafish si:ch211-147a11.3 (20% identical).
Diseases named in the same sentence as C1orf174 in open-access papers:
C1orf174 is named in the same sentence as 1 disease in open-access papers, as found by Europe PMC text mining. Sharing a sentence is not in itself a finding about the gene and the disease. The quoted sentences say what the papers report.
cancer (1 paper, 2018). A tumor composed of atypical neoplastic, often pleomorphic cells that invade other tissues. "Also chosen were two randomly selected ARA-lincRNAs that are neighbors of C1orf174 and GNPTAB, which have not been related to any cancer, however, they encode proteins that are shown at The Human Protein Atlas3 as being possible prognostic markers of a number of cancers." (PMID 29875794, 2018).